CDK4 (cyclin dependent kinase 4)
Diseases named in the same sentence as CDK4 in open-access papers (continued):
Sharing a sentence is not in itself a finding about the gene and the disease.
melanoma (continued). "Regarding tumor suppressors, CDKN2A, the CDK4/6 inhibitor, which is deleted or mutated in 40% of melanomas, and the PI3K/AKT pathway inhibitor, which exhibits characteristic loss of function in 20–30% of melanomas, were considered." (PMID 40647405, 2025). "In melanoma, CDK4/6 inhibitors not only suppress tumor growth but also enhance anti-tumor immunity." (PMID 40430484, 2025). "The LOGIC-2 trial (NCT02159066) evaluated the efficacy of adding one of four other agents including ribociclib (CDK4/6i) to encorafenib (BRAFi) and binimetinib (MEKi) in 38 patients with advanced BRAF V600-mutated melanoma who progressed on encorafenib and binimetinib." (PMID 40282469, 2025). "Notably, the anti-proliferative effect of REDD2 was comparable to that of the expression of CDKN2A-p16; a well-established tumor suppressor, which blocks the cell cycle by inhibiting CDK4 and CDK6 and is frequently deleted or mutated in melanoma." (PMID 40918647, 2025). "Another study revealed that combined exposure of melanoma cells to metformin (1 mM) and binimetinib (2 μM) showed a reduced number of cells undergoing S phase replication compared to the control and led to G0/G1 arrest through the cyclin D/CDK4/CDK6 pathway." (PMID 41373567, 2025). "Based on the observation that the CDK4/6 pathway is frequently altered in melanoma, CDK4/6 inhibitors have emerged as potential agents for treating patients with NRAS-mutant and BRAF-wild-type tumors that have not lost the tumor suppressor retinoblastoma protein (pRb)." (PMID 40904502, 2025). "In addition, CDK4 and CCND1, cell cycle regulators that are frequently mutated or amplified in BRAF wild-type melanomas, were included." (PMID 40647405, 2025). "The aim of the present work was to identify potential pathogenic germline genetic variants in melanoma‐prone families without any detected pathogenic alterations in CDKN2A or CDK4." (PMID 40072281, 2025). "Similarly, coculture assays of melanoma cells with CDK4/6 inhibitor-treated fibroblasts promoted the growth of neoplastic cells in diverse preclinical models and suppressed antitumour immune responses." (PMID 41388212, 2025). "While early stage (I-IIA) melanoma has 5-year overall survival rates of greater than 90%, it worsens in more advanced disease Melanoma arises in melanocytes due to a combination of genetic predisposition (CDKN2A, CDK4) and acquired mutations (BRAF, MEK) from ultraviolet light-induced damage." (PMID 39602056, 2024). "Moreover, it was demonstrated that CDK4/6 pathway is correlated to a potential resistance mechanism to anti-PD1 therapy in melanoma and increased activity of the CDK4/6 inhibitor CDKN2A correlates with response to PD-L1 blockage in RCC and NSCLC patients." (PMID 38983859, 2024). "Moreover, we observed that CDK4/6 inhibition represses a cancer cell programme shown to mediate resistance to anti‐PD1 therapy in melanoma, consistent with studies demonstrating a cooperation between CDK4/6i and immune checkpoint blockade." (PMID 36453028, 2024). "Another point of interest is the significant potential of CDK4/6 inhibitors in melanoma treatment." (PMID 39200315, 2024). "For instance, cellular senescence induced by CDK4/6-targeted drugs in melanoma was shown to repress a resistance program expressed by malignant cells prior to immunotherapy, which is associated with T cell exclusion and predicts unfavorable clinical response to anti-PD-1 therapy." (PMID 39126015, 2024). "The results showed that as the melanoma progressed, the expression of malignant progression marker genes (pmel, mlana, sox10, cdk4, zeb1, and vim) significantly increased, with notable expression differences observed among benign nevi, dysplastic nevi, and invasive melanoma." (PMID 39659584, 2024). "Moreover, loss of keratinocytic RXRα, a dimeric partner of VDR, combined with activated CDK4 or oncogenic NRAS generated UVB-induced melanomas." (PMID 38927967, 2024).
melanoma (continued). "These trials may support the clinical application of CDK4/6 inhibitors in treating melanoma patients with CDKN2A deletion." (PMID 38534309, 2024). "Sometimes, acral lentiginous melanoma cells acquire resistance to CDK4/6 inhibitors." (PMID 39598629, 2024). "The ribociclib and binimetinib combination has demonstrated effectiveness in NRAS‐mutated melanoma, especially in patients with additional cell cycle gene mutations (CDKN2A, CDK4, and CCND1), who may derive greater benefit from this therapy." (PMID 39564955, 2024). "Importantly, CDK4/6 inhibition repressed this T cell exclusion program and enhanced immunotherapy response in pre-clinical melanoma models." (PMID 38241976, 2024). "This study revealed that targeting MDM2 in combination with CDK4/6 inhibitors could enhance the therapeutic efficacy and overcome resistance in melanoma cells." (PMID 39200315, 2024). "In accordance with this, high CDK4 expression was also observed in the melanoma tissue compared to the healthy skin tissue and was similarly also increased in expression in primary melanoma when compared to metastatic melanoma—the pattern previously observed with hsa_circ_0025039 and miR-198." (PMID 38672402, 2024). "Additionally, therapy resistance remains a hurdle in treating metastatic melanoma patients, and even though the CDK4/6 pathway is often dysregulated in melanoma patients, clinical data have suggested an intrinsic resistance of melanoma to CDK4/6 inhibitors." (PMID 38238702, 2024). "Further research is needed to establish the effectiveness of dalpiciclib and other CDK4 inhibitors, which may have widespread utility in melanoma at various anatomical locations." (PMID 38807144, 2024). "Germline mutations of CDKN2A, CDK4, TERT, and POT1 genes have been identified as high-risk factors for melanoma susceptibility, whereas MC1R (melanocortin 1 receptor) polymorphic variants are reported in 60.5–82.1% of melanoma." (PMID 38473275, 2024). "Several studies have indicated that inhibition of CDK4 pathway activity may be a potential therapeutic option for melanoma, including MM." (PMID 38807144, 2024). "The CDK4/CDK6 pathway is frequently dysregulated in melanoma, leading to excessive proliferation." (PMID 36765875, 2023). "When CDK4 is overexpressed, it can lead to an excess of these phosphorylated proteins, which can result in an acceleration of the cell cycle and an increase in the proliferation of melanoma cells." (PMID 37504268, 2023). "Moreover, bioinformatics analysis confirmed the interactions between the kynurenine pathway, cyclin D1, and CDK4 in melanoma." (PMID 37245164, 2023). "Even though POT1 seems to be the second major melanoma susceptibility gene, with 2%–4% of CDKN2A/CDK4-WT families carrying a pathogenic coding variant in this gene, its contribution to melanoma risk burden in the general population is minor, with ~0.5% of cases carrying pathogenic variants." (PMID 36539277, 2023). "The purpose of this study was to perform a mutational analysis of the seven candidate melanoma susceptibility genes (ACD, BAP1, MC1R, MITF, POT1, TERF2IP, and TERT) in high-risk melanoma patients (familial melanoma and MPM) from southeastern Brazil, besides the CDKN2A and CDK4 genes." (PMID 37958811, 2023). "While preclinical and clinical evidence suggests a potentially favorable impact of CDK4/6 inhibitors on this condition, further investigations are essential in the realm of personalized medicine for individuals with hereditary pancreatic cancer and melanoma." (PMID 38137564, 2023). "Increased genetic risk for melanoma can occur in the context of germline pathogenic variants in high-penetrance genes, such as CDKN2A and CDK4, risk variants in low- to moderate-penetrance genes (MC1R and MITF), and possibly due to variants in emerging genes, such as ACD, TERF2IP, and TERT." (PMID 37958811, 2023).
melanoma (continued). "For the primary melanoma cell line—WM3211 (VGP), with a wild type for BRAF, PTEN, N-RAS, and CDK4, and with a mutation at position 576 in the c-KIT gene, caspase 3 activation compared to the control was several times lower than for the metastatic lines Mel-1359 and MEWO." (PMID 37097377, 2023). "CDK4 inhibitors have been studied as potential treatments for melanoma." (PMID 37504268, 2023). "Let-7 family is generally down-regulated in melanoma, and let-7b, a member of this family, has been reported to directly target cyclin D1 controlling cell cycle progression by activating cyclin-dependent kinases 4 and 6 (CDK4/6)." (PMID 38070141, 2023). "Clinical application of CDK4/6 SMIs appears to display weak effects in some tumors (including colorectal cancer, triple-negative breast cancer, melanomas, etc.), where innate or rapid acquisition of resistance may happen." (PMID 35327487, 2022). "In the case of melanoma, CDK4/6i have shown efficacy in vitro, while the success in clinical trials has been moderate or still under evaluation, making it a cancer in which the treatment could be improved by dual senolytic therapy." (PMID 35158840, 2022). "For example, B-Raf is targeted by dabrafenib and vemurafenib, MEK1/2—by trametinib (widely used in melanomas), CDK4—by abemaciclib, palbociclib and ribociclib in breast cancer, Bcr-Abl are targeted by dasatinib and imatinib in CML, erlotinib and gefitinib target EGFR in lung cancers (NSCLC)." (PMID 35455007, 2022). "Examining our human melanoma specimens with patient-matched normal tissue, we found that FAK was primarily inactive and nuclear localized in normal skin, which was associated with low levels of CDK4." (PMID 35525274, 2022). "Considering CCND1 is an important driver of CDK4, CDK4/6 inhibitors as monotherapy or in combination with ICIs may represent a highly promising treatment for patients with melanoma harboring CCND1 amplification." (PMID 35844619, 2022). "Altogether, mutations in these genes, associated with CDK4, TERT promoter, and MITF, are found in < 3% of melanoma-prone families in studied populations, and the majority (>70%) of familial cases are of unknown etiology." (PMID 35085295, 2022). "CDKN2A, along with CDK4, TERT, and POT1 genes, are high-risk genes for melanoma." (PMID 35465855, 2022). "CDK4 expression was also elevated within the melanoma lesion." (PMID 35525274, 2022). "However, IL6 expression remains dependent on AKT1 and STING, suggesting that the regulation of individual SASP factors in response to CDK4/6 inhibition in melanoma cells is complex, with compensatory mechanisms we have yet to elucidate." (PMID 35158840, 2022). "In melanoma, the upregulation of hsa_circ_0025039 induced the downregulation of miR-198, thus promoting cancer progression by de-repressing cyclin-dependent kinase 4 (CDK4)." (PMID 34314379, 2021). "Importantly, these results suggest that CDK4/6 inhibition reprograms mitochondrial metabolism and induces mitochondrial biogenesis in melanoma cells, in agreement with studies in other cancer models." (PMID 33572972, 2021). "Furthermore, HSPB8 in melanoma cell lines and primary melanoma tissues is expressed at levels higher than normally found in melanocytes, and this could be related to the activation of growth-associated transcription factors, such as E2F and/or cyclin-dependent kinases (cdk), such as cdk4." (PMID 33562660, 2021). "Three of the four tested melanoma cell lines were sensitive to the CDK4/6 inhibitor." (PMID 34485433, 2021). "Hence both cell lines provide a mechanistic rationale for the addition of CDK4/6 inhibitor in melanoma." (PMID 34944961, 2021). "Melanoma genes were found to be sensitive to CDK4 inhibitors in vivo." (PMID 34422248, 2021). "Moreover, using four canine melanoma cell lines, we explored the possibility of blocking the Rb-E2F pathway by using a CDK4/6 inhibitor (Palbociclib) as a potential anti-cancer therapy." (PMID 34485433, 2021).
melanoma (continued). "In addition to the MAPK pathway, deregulation of cyclin-dependent kinase 4 and 6 (CDK4/6) activity frequently occurs in melanoma, mainly due to inactivation of the CDK4/6 inhibitor p16INK4A via gene deletion, somatic mutation, or promoter hypermethylation." (PMID 33572972, 2021). "Alterations in the CDKN2A pathway in melanomas can occur due to either copy number changes (deletions of CDKN2A, the amplification of CCND1, and the amplification of CDK4/6), mutations in CDKN2A or CDK4/6, and promoter hypermethylation of CDKN2A." (PMID 34831002, 2021). "Due to the high expression of E2F target genes in canine melanoma tissue samples, we further investigated the possibility of targeting the Rb-E2F pathway, as a new potential anticancer therapeutic approach for canine oral melanoma using a CDK4/6 inhibitor." (PMID 34485433, 2021). "However, one canine melanoma cell line (CMM12) was resistant to CDK4/6 inhibition of proliferation and G1 cell cycle arrest." (PMID 34485433, 2021). "The present results suggest that CDK4/6 inhibitors could potentially be used as a new anti-cancer treatment for canine melanoma and that H2AFZ could serve as a prognostic and predictive marker for patient selection." (PMID 34485433, 2021). "Since the CDK4/6 pathway is frequently dysregulated in melanoma, it could be anticipated that CDK4/6 inhibitors have a high degree of activity against this disease." (PMID 34071228, 2021). "Another study reported that CDK4 copy number gain was negatively correlated with anti-PD1 response in all subtypes of advanced melanoma and CCND1 copy number gain was associated with a lack of response to anti-PD-1 therapy in advanced acral melanoma." (PMID 34221994, 2021). "KYN decreased the protein level of CDK4 and increased cyclin D1 in melanoma SK-MEL-3 cells." (PMID 34299117, 2021). "The anti-tumor efficacy of single agent CDK4/6 inhibitors is unknown in melanomas bearing specific dysregulations in the CDKN2A pathway." (PMID 34831002, 2021). "CDK4 pathway is a frequently altered signaling in melanomas." (PMID 34071228, 2021). "Also, amplification of CDK4 has been reported in melanoma, glioma, rhabdomyosarcoma, and lung cancer and confers resistance to CDK4/6 inhibitors in these malignancies." (PMID 34123801, 2021). "Moreover, it has been recently reported that CDK4/6 axis is a tumor-intrinsic resistance mechanism to anti PD1 therapy in melanoma and increased activity of the CDK4/6 inhibitor CDKN2A correlates with response to PD-L1 blockage in RCC and NSCLC patients." (PMID 34299136, 2021). "Indeed, treatment of melanoma cell cultures cells with CDK4 inhibitor palbociclib reduced cell proliferation to a similar extent as MAPK inhibitors." (PMID 33535416, 2021). "In addition, PTEN and FAT1 loss were recently found to be involved in mediating CDK4/6i resistance in breast cancer, and the PRMT5-MDM4 signaling axis was reported to be involved in determining the response of melanoma to CDK4/6i treatment." (PMID 34508104, 2021). "Collectively, these data suggest that combining mTOR inhibitors and/or MDM2/MDM4 inhibitors might overcome the intrinsic resistance to CDK4/6 inhibitors in melanoma." (PMID 34071228, 2021).
melanoma (continued). "Notably, the mTOR pathway can also activate fatty acid oxidation pathways; thus, we explored the role of MYC and mTOR signalling in metabolic reprogramming following CDK4/6 inhibition in the context of melanoma cells." (PMID 33572972, 2021). "Thus, CDK4/6 inhibitors are potential candidates for therapy of melanoma especially as our data show in combination with RT." (PMID 34722291, 2021). "High levels of CDK4 are common in sarcoma, glioma and melanoma." (PMID 33255177, 2020). "While a mutant form of CDK4 associated with insensitivity towards the inhibitory INK4 proteins is found in familiar melanoma, no mutations have been identified so far in CDK6." (PMID 33255177, 2020). "In bladder cancer cells, a decrease of CDK-2 and cyclin E was also observed, whereas a decrease of cyclin D2 appears in B cell malignancies and melanoma cells, and a decreased expression of CDK4, CDK6, and cyclin E could be found in adult T-cell Leukemia." (PMID 33291743, 2020). "A previous study revealed that targeting CDK4/6 could overcome MAPK-mediated resistance to B-RAF inhibitors in B-RAF V600E melanoma." (PMID 32792963, 2020). "Notably, cyclinD1/CDK4 also induces MEP50 phosphorylation which increases PRMT5 activity, and correspondingly, melanoma that were treated with CDK4/6 inhibitor and developed resistance also exhibited high PRMT5 activity." (PMID 32743345, 2020). "The first involvement of a CDK in a rare disease, familial melanoma, was reported more than 25 years ago, with the discovery of pathogenic mutations in the CDKN2 gene that codes for an inhibitor of CDK4, soon followed by the discovery of mutations in the CDK4 gene itself." (PMID 32762766, 2020). "The genetic alterations such as copy number variations of CDK4 pathway-related genes differ in Asian and Western melanoma which may contribute low response in Asian melanoma." (PMID 32582554, 2020). "Interestingly, we did not observe significant changes in the protein level of cyclin D1 and CDK4 in melanoma A375 and RPMI7951 cells exposed to FICZ." (PMID 33114713, 2020). "In a study of CDKN2A/CDK4 wild-type melanoma-prone families recruited from Australia, UK and the Netherlands, four pedigrees were found (3.8%, n = 4/105) in which melanoma co-segregated with POT1 germline variants (p.Tyr89Cys, p.Gln94Glu, p.Arg273Leu, and c.1687-1G > A)." (PMID 32987645, 2020). "Thus, we studied the effect of KYN, KYNA and FICZ on the protein level of cyclin D1, CDK4 and Rb phosphorylation in melanoma A375 and RPMI7951 cells." (PMID 33114713, 2020). "Applying this platform in melanoma cell lines to profile the immunopeptidome response to CDK4/6 inhibition and interferon-γ — known modulators of antigen presentation — uncovers treatment-specific alterations, connecting the intracellular response to extracellular immune presentation." (PMID 32488085, 2020). "Recently, PRMT5 was shown to be involved in drug resistance against CDK4/6 inhibitors in melanoma." (PMID 32183388, 2020). "CCND1 amplification has been observed in 20–38% of melanoma samples, which indicates that a large group of patients is potentially resistant to BRAFi and could benefit from treatment with a CDK4/6 inhibitor." (PMID 32605090, 2020). "Indeed, p16INK4a regulates cell cycle via the CDK4/Rb-dependent pathway, and modulates mitochondrial dynamics and cell motility in mouse fibroblasts and human melanoma cells." (PMID 32330121, 2020).